RN7SL459P (RNA, 7SL, cytoplasmic 459, pseudogene)
Gene: Miscellaneous RNA gene on chromosome 12 (19,176,288 to 19,176,589, reverse strand). Ensembl gene ENSG00000240993.
Homologues: Orthologues: chimpanzee Metazoa_SRP (97% identical), macaque Metazoa_SRP (90% identical). Paralogues in human: RN7SL1 (77% identical), RN7SL3 (77% identical), RN7SL2 (76% identical), RN7SL336P (76% identical), RN7SL679P (75% identical), RN7SL296P (75% identical), RN7SL478P (75% identical), RN7SL88P (74% identical), RN7SL122P (74% identical), RN7SL220P (74% identical), RN7SL357P (74% identical), RN7SL475P (74% identical), and 701 more.